TTF1 (transcription termination factor 1)
Diseases named in the same sentence as TTF1 in open-access papers (continued):
Sharing a sentence is not in itself a finding about the gene and the disease.
tumor (continued). "In synchronous LUAD brain metastases, TTF-1 negativity reflects an aggressive phenotype with larger proliferation capacity and tumor volume." (PMID 39630375, 2025). "Tumors of the posterior hypophysis and infundibulum represent a family of neoplasms characterized by the expression of thyroid transcription factor‐1 (TTF‐1)." (PMID 39350562, 2025). "Tumor cells in the epithelial component test positive for keratin, epithelial membrane antigen, and TTF‐1." (PMID 40575627, 2025). "Some of them heterogeneously expressed HNF4α and TTF-1, which were mutually exclusive within the same tumor." (PMID 38710944, 2025). "Subsequently, we adopted a diagnostic approach incorporating CK7, CK14, CK18, CK20, and TTF-1 to aid in tumor origin determination." (PMID 40313249, 2025). "The tumor samples with isolated TTF1 positivity were reflective of the presence of normal alveolar cells in the lungs, rather than positive tumor staining." (PMID 40327401, 2025). "The tumor also formed cellular islands; the central area consisted of thyroid transcription factor-1 (TTF-1)-positive adenocarcinoma cells, while the margins contained p40-positive and TTF-1-negative squamous cells." (PMID 41235006, 2025). "Intriguingly, we observed an inverse correlation between TTF-1 status and tumor edema, while tumor volume and edema volume of the dominating brain metastasis as such did not correlate significantly with each other." (PMID 39630375, 2025). "Beyond its critical functions in normal lung, TTF-1 exerts both oncogenic and tumor-suppressive roles in LUAD." (PMID 40824335, 2025). "The follicular areas of the tumor were positive for thyroglobulin, thyroperoxidase, TTF1, and PAX8, supporting a follicular lineage, while the meaning of the morular structures is intriguing." (PMID 40892116, 2025). "How TTF-1 expression affects the immune context in LUAD was investigated, focusing on tumor-associated macrophages (TAMs) and T-cell infiltration." (PMID 40824335, 2025). "TTF-1 maintains alveolar type-II lineage programs and surfactant genes; amplification or overexpression creates lineage dependency that supports tumor fitness." (PMID 41154602, 2025). "The histopathological features of tumor cells, characterized by prominent granular and eosinophilic cytoplasm, aid in distinguishing GCTs of the neurohypophysis from other TTF-1-positive tumors." (PMID 40860841, 2025). "Biopsy confirmed metastatic lung adenocarcinoma, with histopathology showing moderately differentiated tumor cells positive for TTF-1 and Napsin A and weak PD-L1 expression in 15%–20% of cells." (PMID 40708867, 2025). "In these cases, HNF4α and TTF-1 were expressed heterogeneously and were mutually exclusive within the same tumor." (PMID 38710944, 2025). "In the multivariable analysis, tumour stage emerged as the unique factor with independent prognostic impact (p = 0.004) on OS; however, a trend for TTF-1 expression, age, and histological subtype effects was detected." (PMID 37775725, 2024). "In tumor marker-positive 3D models, we detected single cells positive for TTF-1 or p40/p63 in the cancer colony." (PMID 38115596, 2024). "Thyroglobulin, thyroid transcription factor-1 (TTF-1), and other thyroid markers are commonly expressed by the tumor cells." (PMID 38947607, 2024). "TTF‐1 levels were much higher in tumor‐like sites than in normal tissue sites, especially in Group B, indicating the reliability and fidelity of this genetically engineered mouse model (GEMM)." (PMID 39206814, 2024). "We obtained a comprehensive picture of NSCLC transcriptional program downstream TTF1 and p40 that was relevant to prognosis, suggesting a more unifying description of existing subtypes, beyond tumor morphology." (PMID 38291083, 2024). "In this study, we therefore evaluated TTF-1 expression in more than 17,000 tumor tissue samples from 152 different tumor types and subtypes as well as 76 different non-neoplastic tissue types by IHC in a tissue microarray (TMA) format." (PMID 39377914, 2024).
tumor (continued). "Comparing the data of the pathology report (see TTF-1/p63/p40 expression) with the staining results of the original tumor biopsies, in 11 out of 14 tumor biopsies, the marker expression was consistent with the pathology report." (PMID 38115596, 2024). "Overall, 82 (53.9%) of 152 tumor categories showed detectable TTF-1 expression with 42 (27.6%) tumor categories including at least one case with strong positivity." (PMID 39377914, 2024). "Per the outside report, immunostains of tumor cells reported diffusely positive for thyroid transcription factor 1 (TTF-1), high-molecular-weight cytokeratin, and low-molecular-weight cytokeratin." (PMID 39318937, 2024). "The expression of thyroid transcription factor 1 (TTF1) and p63 in tumor cells was observed by immunofluorescence staining." (PMID 39735556, 2024). "The positive expression rate and protein expression of TTF1 and p63 in mouse tumor tissues were evaluated by immunohistochemistry and western blot assays." (PMID 39735556, 2024). "In contrast, the proportion of TTF1-positive and p63-positive cells in the total tumor cells in the treatment groups presented a decreasing trend compared with the model group." (PMID 39735556, 2024). "Among the DECT parameters, AEF, an indicator of tumor blood flow, emerged as a positive predictor of TTF-1 expression." (PMID 39456114, 2024). "In these cases, p63 stained 25 to 75% tumor cells while TTF1 staining pattern ranged from 10 to 80% tumor cells." (PMID 39584166, 2024). "In such cases, the expression of tumor protein (p63) in a diffusely positive TTF-1 tumor should be supportive of adenocarcinoma." (PMID 39070322, 2024). "Tumor cells exhibited a strong nuclear signal for TTF-1, which contrasted with the restricted expression of the control specimens." (PMID 38698774, 2024). "The differential expression of SOX10, GATA3, and TTF-1 is usually helpful in determining the tumor origin." (PMID 38813332, 2024). "TTF-1 exhibits positive staining in cases of adenocarcinoma; however, its expression is seen to decline inversely with tumor differentiation, i.e., with lesser expression in poorly differentiated tumors." (PMID 39070322, 2024). "The comprehensive evaluation of more than 15,000 tumors identified several further tumor entities with frequent TTF-1 positivity some of which were previously underrecognized." (PMID 39377914, 2024). "Of note, any difference in TTF-1 expression according to the laterality of the primary tumour was observed." (PMID 37775725, 2024). "These diversified expression patterns in the ATC tumor were also reported in other clinical studies, while transcription factor TTF-1 is only expressed in 5.7% of ATCs." (PMID 38500204, 2024). "As expected, positivity for TTF1 was observed in most cases (n = 36; 95%), while expression in tumor cells was detected in half of the cases studied, with expression not being associated with LB positivity." (PMID 37510091, 2023). "Immunohistochemistry (IHC) revealed that the tumor cells in this lesion were positive for TTF-1, thyroglobulin, CK19, HBME-1, Galectin-3 and BRAF (V600E)." (PMID 37544981, 2023). "The tumor cytochemistry markers TTF1, CK7, and napsin A were investigated in the studied patient cases." (PMID 38008767, 2023). "Only an extensive immunohistochemical investigation, including the markers CDX2, TTF-1 and ISLET-1, was shown to be significantly associated with the identification of a primary tumor site." (PMID 37686593, 2023). "Among CDX2, TTF-1 and ISLET-1, which correlate with an intestinal, pulmonary or pancreatic origin of the tumor, the expression of TTF-1 was most frequently determined (67%), followed by CDX2 (58%) and ISLET-1 (35%)." (PMID 37686593, 2023).
tumor (continued). "Specifically, untreated patient tumor (TTF1 + /P40 + ) and P3 of the untreated PDX tumor (TTF1−/P40+) was used for analysis." (PMID 37634047, 2023). "Similar to the lung ACs seen in WT mice treated with urethane and HDM, strong nuclear staining for TTF-1 was observed in tumor cells of grade 3 lesions from HDM-treated KrasG12D mice." (PMID 36670473, 2023). "Immunohistochemistry analysis revealed a positive CK7 and TTF1 reaction within the tumour cells and a Ki67 proliferation marker of 55%." (PMID 37627957, 2023). "Our patient’s staining pattern was PAX-8( +)/TG( −)/TTF-1( −)-supported RCC as the origin of the tumor." (PMID 37990226, 2023). "For the metastatic MLA in the lung in case 3, the tumor cells were positive for PAX8, GATA3, and TTF1, in accordance with the immunoprofile of the primary tumor of the uterine corpus." (PMID 35865471, 2022). "On similar grounds, gland formation, identification of mucin in at least five tumour cells by special stains such as Alcian blue and/or immunopositivity with Thyroid transcription factor 1 (TTF-1) enables the correct diagnosis of adenocarcinoma." (PMID 36200017, 2022). "In agreement with cell‐based experiments, the immunofluorescence staining of the LLC‐allograft tumor section revealed a substantial decrease in TTF1 and CD206 expression levels, implying the effective elimination of LLC cells and TAMs." (PMID 35988145, 2022). "Tumour morphology was evaluated, and IHC for TTF-1, Napsin A, CK-7, P-63, P-40, and CD-56 was performed in two steps." (PMID 36712764, 2022). "Pink mucin staining is minimal in the SCC specimen which also shows p40 positive cells, and mucin production is evident in the ADC specimen in agreement with the presence of TTF-1 positive tumor cells." (PMID 34963687, 2022). "Compared to the vehicle group, a TTF1-NP-treated mice group showed a smaller tumor size and reduced STAT3 and p-STAT3 protein expression." (PMID 36296934, 2022). "Immunohistochemically, the tumor cells were positive for syn, CR, CgA, and vasopressin and were focally positive for NeuN, TTF-1, NF, CK8, vimentin, and S100 proteins." (PMID 35663322, 2022). "Immunohistochemical staining showed that tumor cells were diffusely positive for TTF-1, CK7, NapsinA and other alveolar epithelial markers, and negative for CK5/6, P63 and neuroendocrine markers." (PMID 36229884, 2022). "Tumor cells expressed TTF1, PAX8, and p63, NUT protein expression was “equivocal,” and there was no expression of thyroglobulin." (PMID 34997561, 2022). "Tumour grade and type were determined using H&E and immunohistologic stainings against Ttf‐1 and Pcna." (PMID 35364627, 2022). "The organoids showed positive staining of TTF-1, Napsin A, and panCK, suggesting the consistency with original tumor tissues." (PMID 36712673, 2022). "The result was suggestive of a mesenchymal tumor constituted by spindle cells and vascular clefts, showing positivity for endothelial markers and negativity for thyroglobulin, calcitonin and TTF1." (PMID 35612841, 2022). "As expected, tumors obtained from HCC827 tumor cells were differentiated (glandular differentiation is seen, which is pathognomonic of adenocarcinoma) with positive TTF-1 staining." (PMID 36077622, 2022). "Immunohistochemically, the tumor cells were positive for synaptophysin, chromogranin A, and calretinin and were focally positive for NeuN, TTF1, NF, CK8, vimentin, and S100 proteins." (PMID 35663322, 2022). "Sample LF09 (mucinous, mainly lepidic ADC) expressed CK7 at the primary tumor, but lost its expression in successive passages, including the first passage (X0), although it maintained TTF-1 expression in all the passages." (PMID 34198671, 2021). "These cases also exhibited positivity for TTF-1 in the same tumor cells and showed a typical growth pattern of adenocarcinoma." (PMID 33933015, 2021).
tumor (continued). "Mutations of TTF1, MTOR, and BAI3 and deletions of CDKN2A were cross-validated to be enriched in the micropapillary tumor components using Asian and European patient cohorts." (PMID 34221970, 2021). "Diffuse positivity for both P63 and TTF‐1 in Case 5 suggested that the tumor cells were derived from basal cells or have the characteristics similar to basal cells of the bronchiolar epithelium." (PMID 34409758, 2021). "The metastasis was histologically identical to his primary tumor (uniformly tubular and TTF1-positive)." (PMID 33506327, 2021). "Tumor cell nuclei were positive for thyroid transcription factor-1 (TTF-1), and Tg was positive in the cytoplasm of tumor cells and intrafollicles." (PMID 34301330, 2021). "Immunohistochemical analysis showed that the tumor was positive for TTF-1, Napsin-A (focal), P63 (partial) and CK5/6(a few)." (PMID 34663408, 2021). "Thyroid transcription factor 1 (TTF1) staining was also used to confirm presence of cancer cells in the tumor specimens." (PMID 33764690, 2021). "Variable-sized microscopic areas showing a complete lack of TTF1 staining were clearly demarcated from the surrounding tumor cell clusters that were strongly positive for TTF1." (PMID 34829389, 2021). "The follicular epithelial origin of this tumor should be confirmed using immunohistochemistry including positivity for thyroglobulin (inset), thyroperoxidase, TTF1, PAX8, and cytokeratins (clone AE1/AE3)." (PMID 32632840, 2020). "The expression of TTF-1 tended to be at a low level in cells of tumor nodules showing the solid pattern in the KC model." (PMID 33348616, 2020). "The GFP+ tumor cells in both KC and AC models expressed TTF-1, a clinically established LUAD marker." (PMID 33348616, 2020). "No study has evaluated PD-L1 expression in different SCLCs based on tumor location, TTF-1 expression, and specimen types so far." (PMID 33585516, 2020). "The mechanism of TTF1 action included inhibition of tumor angiogenesis and induction of tumor cell apoptosis." (PMID 33716724, 2020). "When this SCLC cohort was divided into good and poor prognosis groups, TTF‐1‐regulated genes were significantly enriched in the poor prognosis group, which also suggested the tumor‐promoting role of TTF‐1 in clinical SCLC tumors." (PMID 31782890, 2020). "Immunohistochemical analyses of the tumors from the original patient sample and subsequent passages in SRG rats revealed comparable expression of p40 and thyroid transcription factor 1 (TTF1) confirming that the tumor maintained its histology in vivo." (PMID 33027304, 2020). "The immunohistochemistry (IHC) analyses showed that tumor cells were positive for thyroid transcription factor-1 (TTF-1) and neuroendocrine markers, including chromogranin A, synaptophysin, INSM1 (insulinoma-associated protein 1), and CD56." (PMID 33352665, 2020). "The tumor cells were immunoreactive for TTF1, thyroglobulin, thyroperoxidase, CK18, HBME-1, and vimentin." (PMID 32632840, 2020). "In order to further study the molecular mechanism of its inhibitory effect on tumor angiogenesis, cam method was used to determine the angiogenesis inhibitory effect of TTF1." (PMID 33716724, 2020). "By immunohistochemistry, the tumor cells are positive for high- and low-molecular-weight keratins and usually positive for thyroglobulin, TTF1, and PAX8." (PMID 32632840, 2020). "The largest lesion located in the pancreatic head was a moderately proliferating G2 tumor (Ki-67: 8%; TTF1 positiv) 30 mm in diameter (pT2)." (PMID 30795813, 2019). "In two of these cases (cases 1 and 3), p40‐positive tumor cells expressed TTF‐1, SYN, CD56, and CK5." (PMID 30957413, 2019). "TTF-1 knockdown via RNA interference in these adenocarcinoma cell lines substantially induced tumor growth inhibition and apoptosis." (PMID 31196060, 2019).
tumor (continued). "The TMP panel included 7 proteins routinely used in diagnostic IHC including cytokeratins (KRT5 and KRT7), markers of stratified epithelia (P63), mesenchymal (Vimentin) and neuroendocrine (CHGA, SYP) differentiation, and primary tumour origin (TTF1)." (PMID 31537838, 2019). "In the remaining five cases, 1–5% of tumor cells expressed p40, and in three of these, the cells expressing p40 also expressed TTF‐1 and neuroendocrine markers." (PMID 30957413, 2019). "The tumor cells were positive for TTF1, PAX8 and thyroglobulin, and the proliferation indexes were 4% and 1,9% respectively." (PMID 31699114, 2019). "Immunhistochemical analyses were performed, and the tumor cells were uniformly positive for TTF1, CK19 and Bcl-2." (PMID 29976183, 2018). "Spheres from tumor 26 were positive for chromogranin A (CgA) and TTF-1 expression, reflecting the SCLC/neuroendocrine phenotype of their tumor of origin." (PMID 29503225, 2018). "Membranous C-RAF and HA tag along with strong nuclear c-MYC and TTF-1 were detected in the tumor cells." (PMID 29464089, 2018). "The tumor cells were also positive for TTF-1, which is a biomarker for follicular epithelium carcinoma of the thyroid." (PMID 30424779, 2018). "Cancer cells in the pleural effusion of case 1 were immunopositive for thyroid transcription factor (TTF)-1, while tumor tissue in case 5 was positive for TTF-1." (PMID 29844868, 2018). "The mechanisms by which TTF-1 and its transcriptional activity are related to tumor aggressiveness are not fully understood." (PMID 29079814, 2017). "The tumor cells were positive for thyroid transcription factor-1 (TTF-1) on immunohistological staining." (PMID 29237502, 2017). "Peritoneal effusion and peritoneum biopsy were evidenced, and a cytological examination of the ascites found clustered and scattered tumor cells; IHC of peritoneum tissue and ascite tumor cells showed positive for CK-7 and TTF-1." (PMID 28950878, 2017). "In clinical observations, the TTF-1 expression presented reciprocal correlation with the grade of tumor differentiation." (PMID 29079814, 2017). "TTF-1 immunohistochemical staining was positive for the tumor cells, and the mass was diagnosed as poorly differentiated metastatic adenocarcinoma." (PMID 28806950, 2017). "In this study, we investigated the expression profiles of CD73 and A2AR in tumor cells and found that both proteins were more strongly expressed in adenocarcinoma, particularly TTF-1-positive and EGFR-mutant adenocarcinomas." (PMID 28060732, 2017). "When a tumor is positive for TTF-1, it is almost always adenocarcinoma arising from the thyroid or lung." (PMID 29900025, 2017). "The expression of thyroid differentiation markers, TG (thyroglobulin) and TTF1, was maintained in spheroids and was variable, mostly sparse in spheroids from normal tissues or preferentially located in the peripheral area of tumor spheroids." (PMID 28039458, 2017). "There was reduced Ttf1 staining in erlotinib treated EGFRL858R-driven tumors suggesting a decrease in tumor cells originating from type II epithelial cells." (PMID 27494838, 2016). "TTF-1 is a well-established biomarker for the tumor derived from the lung, and in our presented case, TTF-1 was expressed in the breast mass, consistent with a metastasis of lung primary." (PMID 27488410, 2016). "Tenascin C showed a very weak correlation, E-cadherin a weak to moderate correlation, and TTF-1 a strong correlation with tumor proliferation." (PMID 27409604, 2016). "For example, thyroid transcription factor-1 (TTF-1) is a sensitive marker for lung SmCC (positive in 80%–100%), so its absence in tumor cells is of value to exclude a metastatic NEC of the lung." (PMID 27610258, 2016). "Thyroid transcription factor-1 (TTF-1) and TG staining was also positive, confirming the tumor’s ability to differentiate into thyroid tissue." (PMID 27282149, 2016).